SLC25A51 (solute carrier family 25 member 51)
Description:
Mitochondrial membrane carrier protein that mediates the import of NAD(+) into mitochondria. Mitochondrial NAD(+) is required for glycolysis and mitochondrial respiration. Compared to SLC25A52, SLC25A51-mediated transport is essential for the import of NAD(+) in mitochondria. The transport mechanism, uniport or antiport, its electrogenicity and substrate selectivity, remain to be elucidated.
Synonyms: MCART1; MGC14836; CG7943
Tractability: Antibody: UniProt predicts a signal peptide or a membrane-spanning region. PROTAC: its protein half-life has been measured.
Gene: Protein-coding gene on chromosome 9 (37,879,400 to 37,904,387, reverse strand). Ensembl gene ENSG00000122696.
Subcellular location: Mitochondrion inner membrane
Subcellular location (Human Protein Atlas): Mitochondria
Pathways (Reactome):
Metabolism: Nicotinate metabolism
Gene Ontology:
Molecular function: NAD transmembrane transporter activity
Biological process: aerobic electron transport chain; mitochondrial NAD transmembrane transport; nicotinate metabolic process
Cellular component: mitochondrial inner membrane; mitochondrion
Genetic constraint (gnomAD): Loss-of-function variants: 11 observed, 20.06 expected, observed/expected ratio (o/e) 0.55, 90% interval 0.34 to 0.91. The upper end of that interval is the gene's LOEUF score, 0.91, which puts it in group 3 of 6, group 1 being the genes least tolerant of losing a copy. Missense variants: 201 observed, 371.18 expected, observed/expected ratio (o/e) 0.54, 90% interval 0.48 to 0.61. Synonymous variants: 105 observed, 137.03 expected, observed/expected ratio (o/e) 0.77, 90% interval 0.65 to 0.9.
Homologues: Orthologues: chimpanzee SLC25A51 (100% identical), macaque SLC25A51 (99% identical), dog SLC25A51 (93% identical), guinea pig Slc25a51 (89% identical), mouse Slc25a51 (87% identical), rat Slc25a51 (86% identical), rat Slc25a52 (84% identical), rat Slc25a51l1 (79% identical). Paralogues in human: SLC25A52 (96% identical), SLC25A13 (29% identical), SLC25A12 (28% identical), SLC25A21 (26% identical), SLC25A20 (25% identical), SLC25A39 (25% identical), SLC25A16 (25% identical), SLC25A22 (25% identical), SLC25A6 (25% identical), UCP3 (25% identical), SLC25A31 (24% identical), UCP1 (24% identical), and 37 more.
Diseases named in the same sentence as SLC25A51 in open-access papers:
SLC25A51 is named in the same sentence as 18 diseases in open-access papers, as found by Europe PMC text mining. Sharing a sentence is not in itself a finding about the gene and the disease. The quoted sentences say what the papers report.
hepatocellular carcinoma (2 papers, 2023 to 2024). A malignant tumor that arises from hepatocytes. "Previous studies have confirmed that SLC25A51 is significantly overexpressed in human hepatocellular carcinoma (HCC) and enhances glycolysis and HCC progression by activating sirtuin 5 (SIRT5)." (PMID 36902385, 2023).
Obesity (2 papers, 2026). Accumulation of substantial excess body fat. "In conclusion, our results provide novel mechanistic and therapeutic insights into understanding the critical role of adipocyte mitochondrial NAD transporter SLC25A51 in the pathophysiology of age-associated metabolic diseases, particularly obesity and insulin resistance." (PMID 42015379, 2026).
acute myeloid leukemia (1 paper, 2025). Acute myeloid leukemia (AML) is a group of neoplasms arising from precursor cells committed to the myeloid cell-line differentiation. "SLC25A51 increases the mitochondrial NAD+/NADH ratio, thus controlling the proliferation of acute myeloid leukemia cells." (PMID 39754188, 2025).
Hepatic steatosis (1 paper, 2025). Steatosis is a term used to denote lipid accumulation within hepatocytes. "Mice with reduced hepatic Slc25a51 expression exhibit hepatic steatosis and hypertriglyceridemia after fasting." (PMID 40307568, 2025).
lung adenocarcinoma (1 paper, 2025). A carcinoma that arises from the lung and is characterized by the presence of malignant glandular epithelial cells. "Compared to normal lung tissues, SLC25A51 was significantly upregulated in lung adenocarcinoma tissues, with its expression positively correlated with LINC02802." (PMID 40860186, 2025).
lung carcinoma (1 paper, 2025). "To further confirm that SLC25A51 is a downstream target gene of LINC02802 in promoting lung cancer progression, we performed cell biology rescue experiments." (PMID 40860186, 2025). "Our study highlights the critical role of SLC25A51 as a mitochondrial NAD+ transporter that governs key aspects of cellular metabolism in lung cancer." (PMID 40860186, 2025). "Interestingly, either silencing LINC02802 with antisense oligonucleotides (ASOs) or treating cells with fludarabine phosphate, an SLC25A51 inhibitor, successfully reversed cisplatin resistance in lung cancer cells." (PMID 40860186, 2025). "Taken together, these findings indicate that SLC25A51 promotes NSCLC tumor progression, and that targeting SLC25A51 may represent a promising therapeutic strategy for the treatment of lung cancer." (PMID 40860186, 2025). "Importantly, overexpression of SLC25A51 could reverse the inhibitory effects of LINC02802 knockdown on the migration and invasion capacities of lung cancer cells." (PMID 40860186, 2025).
non-small cell lung carcinoma (1 paper, 2025). A group of at least three distinct histological types of lung cancer, including non-small cell squamous cell carcinoma, adenocarcinoma, and large cell carcinoma. "However, the precise role of SLC25A51 in non-small cell lung cancer (NSCLC) remains largely unexplored." (PMID 40860186, 2025).
cancer (4 papers, 2023 to 2025). A tumor composed of atypical neoplastic, often pleomorphic cells that invade other tissues. "Dysregulation of NAD+ metabolism has been increasingly implicated in cancer development and progression, suggesting that SLC25A51 may serve as a critical mediator linking mitochondrial metabolism to tumorigenesis." (PMID 40860186, 2025). "Recent studies on the role of SLC25A51 in cancers, show increased levels of SLC25A51 in multiple cancers, and furthermore loss of SLC25A51 decreased proliferation and apoptosis in two different cancer cell models." (PMID 40179319, 2025). "Dysregulation of mitochondrial metabolism through altered SLC25A51 activity can enhance cancer cell proliferation, survival, and metastatic potential." (PMID 40860186, 2025). "Future therapeutic strategies that inhibit SLC25A51 function or its downstream metabolic pathways could enhance the efficacy of existing cancer treatments and improve patient outcomes." (PMID 40860186, 2025). "Thus, SLC25A51 represents not only a metabolic regulator fundamental to cancer cell fitness but also a promising target to overcome therapy resistance." (PMID 40860186, 2025). "Cancer cells with elevated SLC25A51 expression may sustain mitochondrial function and redox balance, thereby mitigating chemotherapy-induced oxidative stress and apoptosis." (PMID 40860186, 2025). "Thus, SLC25A51 plays a crucial role in cancer metabolism, warranting consideration as a potential drug target." (PMID 39795950, 2024). "Therefore, SLC25A51 is predicted to play a crucial role in cancer pathogenesis by orchestrating cellular metabolism, DNA repair, and epigenetic modifications." (PMID 39795950, 2024). "In summary, SLC25A51 is upregulated in cancer and mediates an increase in mitochondrial NAD+, which in turn contributes to cancer metabolic reprogramming, mainly through modulating sirtuin proteins." (PMID 39795950, 2024). "Another member SLC25A51 from the same family has been shown to be a transporter of NAD+/NADH, and it is speculated that it may be related to the development of cancer by regulating cellular metabolism." (PMID 37550282, 2023).
tumor (3 papers, 2024 to 2025). "SLC25A51 expression was positively associated with tumor size, vascular invasion, and shorter overall and disease-free survival." (PMID 39795950, 2024). "Conversely, targeting SLC25A51 disrupts this metabolic resilience, sensitizing tumor cells to treatment." (PMID 40860186, 2025). "In summary, this evidence partially indicates that LINC02802 functions to promote tumor progression by regulating the expression of SLC25A51." (PMID 40860186, 2025). "By regulating the mitochondrial NAD+/NADH ratio, SLC25A51 directly influences oxidative phosphorylation and energy production, processes that are often reprogrammed during tumor progression." (PMID 40860186, 2025). "Aspirin also potentiated protein hyperacetylation mediated by SLC25A51 KO or fludarabine treatment, significantly reducing tumor cell proliferation and colony formation, as well as inhibiting xenograft growth synergistically with fludarabine." (PMID 39795950, 2024). "Compared to wild-type controls, silencing SLC25A51 in HCC cells led to decreased cell proliferation and colony formation, abrogated cell invasion and migration, and significantly reduced tumor growth in xenograft models." (PMID 39795950, 2024). "It has recently been discovered that SLC25A51 could sustain mitochondria acetylation homeostasis and proline biogenesis by promoting the deacetylation function of Sirtuin 3 (SIRT3), which may ultimately prompt the proliferative capacity of tumor cells." (PMID 38966636, 2024).
SLC25A51 also shares sentences with these, for which no sentence is quoted: colon cancer (1 paper); hypertriglyceridemia (1); Insulin resistance (1); intrahepatic cholestasis (1); liver dysfunction (1); metabolic disease (1); migraine (1); oligospermia (1); renal fibrosis (1).